OR6C74 (olfactory receptor family 6 subfamily C member 74)
Description:
Odorant receptor.
Tractability: Antibody: UniProt places it where antibodies can reach, with medium confidence; UniProt predicts a signal peptide or a membrane-spanning region; its Gene Ontology location is reachable by antibodies, with medium confidence.
Gene: Protein-coding gene on chromosome 12 (55,244,609 to 55,256,625, forward strand). Ensembl gene ENSG00000197706.
Subcellular location: Cell membrane
Pathways (Reactome):
Sensory Perception: Expression and translocation of olfactory receptors
Gene Ontology:
Molecular function: olfactory receptor activity; G protein-coupled receptor activity
Biological process: detection of chemical stimulus involved in sensory perception of smell; G protein-coupled receptor signaling pathway
Cellular component: plasma membrane; membrane
Genetic constraint (gnomAD): Loss-of-function variants: 3 observed, 1.74 expected, observed/expected ratio (o/e) 1.73, 90% interval 0.61 to 1.94. That is too few expected variants to judge how well the gene tolerates losing a copy. Missense variants: 337 observed, 361.21 expected, observed/expected ratio (o/e) 0.93, 90% interval 0.85 to 1.02. Synonymous variants: 139 observed, 134.32 expected, observed/expected ratio (o/e) 1.03, 90% interval 0.9 to 1.19.
Homologues: Orthologues: chimpanzee OR6C74 (99% identical), macaque OR6C74 (96% identical), rat Or6c74 (88% identical), mouse Or6c74 (88% identical), dog OR6C74 (88% identical). Paralogues in human: OR6C75 (72% identical), OR6C76 (72% identical), OR6C6 (70% identical), OR6C2 (69% identical), OR6C65 (69% identical), OR6C3 (68% identical), OR6C1 (67% identical), OR6C4 (67% identical), OR6C70 (66% identical), OR2AP1 (65% identical), OR6C68 (63% identical), OR6M1 (46% identical), and 6 more.